FABP4 (fatty acid binding protein 4)
Diseases named in the same sentence as FABP4 in open-access papers (continued):
Sharing a sentence is not in itself a finding about the gene and the disease.
Obesity (continued). "FABP4 expression in liver has been shown to be significantly elevated in mouse models of obesity-promoted hepatocellular carcinoma and in patients with underlying hepatic steatosis resulting from NAFLD27." (PMID 32205840, 2020). "In contrast, FABP4 mRNA levels were decreasing with the degree of obesity in sc AT and visceral AT of humans." (PMID 32321549, 2020). "Despite the shortcomings of the Fabp4-Cre-mediated Hoxc9 targeting, we found a genotype-phenotype association in male ATHoxc9-/- mice after HFD-induced obesity." (PMID 32610701, 2020). "Five out of the 358 obesity-specific genes, FABP4, CFD, GHR, TNFRSF11B, and LTF, presented significantly decreased expression in TC patients (LFC<−1.44; and p-value < 1e−7)." (PMID 33240576, 2020). "Using the system biology approach, we mined a set of genes influenced by obesity to uncover five genes (FABP4, CFD, GHR, TNFRSF11B, and LTF) as previously unrecognized contributors to the development of TC." (PMID 33240576, 2020). "An involvement of FABP4 in the pathogenesis of obesity and insulin resistance seems to be mediated via FABP4-dependent peroxisome proliferator-activated receptor γ (PPARγ) inhibition." (PMID 30857223, 2019). "As we all know, obesity is a risk factor for CRC, whereas the role of FABP4 and its underlying molecular mechanism in tumorigenesis of CRC have not been elucidated." (PMID 31651326, 2019). "Circulating FABP4 levels are elevated in obesity-related metabolic disorders such as obesity, insulin resistance, diabetes, hypertension, atherosclerosis, and impaired myocardial contractility." (PMID 31208019, 2019). "The fatty acid-binding protein 4 (FABP4) has been correlated with obesity markers, such as high BMI and fat mass, and regulate lipid and glucose metabolism through fatty acid transport and uptake." (PMID 31666083, 2019). "A considerable number of studies have shown that plasma concentrations of FABP4 is increased in obesity and T2DM, and that circulating FABP4 levels are correlated with certain clinical parameters, such as body mass index, insulin resistance, and dyslipidemia." (PMID 30857223, 2019). "It is interesting to note that, although this vesicular FABP4 accounts for only a minor fraction (∼0.5%) of the total secreted pool of FABP4, it is regulated in mouse and human obesity." (PMID 30705117, 2019). "Clinical and animal-based studies have demonstrated that FABP4 functions as a critical mediator of inflammatory process both locally and systemically and has an important role in obesity-related metabolic diseases." (PMID 30401801, 2018). "Mice deficient in FABP4 and FABP5 reveal a striking phenotype with strong protection against diet-induced obesity, insulin resistance, type 2 diabetes and fatty liver disease." (PMID 29850615, 2018). "The same is true for the fatty acid binding protein-4 (FABP4), which is known to be involved in other diseases, such as obesity, diabetes, atherosclerosis and cardiac dysfunction, but to the best of our knowledge has not been studied in context of HCC." (PMID 29363612, 2018). "We did not observe any difference in the plasma concentration of cytosolic FABP4 in subjects with obesity compared to the lean ones (P = 0.09)." (PMID 29335416, 2018). "Adipocyte fatty acid-binding protein (A-FABP; also known as aP2 or FABP4), is a novel adipokine that has recently received considerable attention because it integrates obesity, diabetes mellitus, and atherosclerosis." (PMID 29441065, 2018). "FABP4 is secreted by fat cells and the blood concentration is related to obesity, diabetes, and arteriosclerosis." (PMID 28654680, 2017). "In fact, fatty acid binding protein 4 (FABP4)/IL-6/STAT3/DNA methyltransferase 1 (DNMT1) have been shown to link obesity to the growth of AML cells." (PMID 29269861, 2017). "Therefore, deficiency in serum FABP4 might improve the disorders associated with obesity." (PMID 26752184, 2016).
Obesity (continued). "Enhanced FAO in rBA reduced TG content and FABP4 and TNFa mRNA levels, thereby protecting brown adipocytes from obesity and inflammation." (PMID 27438137, 2016). "Fatty acid-binding protein 4 (FABP4/A-FABP/aP2) is secreted from adipocytes in association with catecholamine-induced lipolysis, and elevated serum FABP4 level is associated with obesity, insulin resistance and atherosclerosis." (PMID 27124282, 2016). "Accumulating evidence has suggested that irisin ameliorates obesity, glucose/lipid metabolic disorders and insulin resistance, in contrast with the metabolic function of FABP4." (PMID 26752184, 2016). "With the current study, we have shown that higher serum FABP4 levels increased the risks of obesity-related metabolic disorders and hypertension." (PMID 26752184, 2016). "The mRNA levels of the obesity (FABP4) and inflammatory (TNFa) markers were increased after palmitate treatment." (PMID 27438137, 2016). "Transgenic mice expressing UCP1 from the fatty acid binding protein 4 (FABP4) promoter are resistant to genetic and diet-induced obesity." (PMID 25364764, 2014). "Previous studies indicated that circulating FABP4 levels are considered to be a link between obesity, insulin resistance, diabetes, and cardiovascular diseases." (PMID 24593955, 2014). "Circulating adipocyte fatty acid-binding protein (FABP4) levels are considered to be a link between obesity, insulin resistance, diabetes, and cardiovascular (CV) diseases." (PMID 23642261, 2013). "Circulating levels of FABP4 are positively correlated with obesity and non-alcoholic fatty liver and predict the development of metabolic syndrome and type 2 diabetes." (PMID 24205333, 2013). "FABP4 takes part in the predisposition of cardiac fats in obese persons, and ADIPOQ upregulation is the main cause of type 2 diabetes and obesity." (PMID 23922792, 2013). "BMS309403 is a biphenyl azole inhibitor against fatty acid binding protein 4 (FABP4) and regarded as a lead compound for effective treatment of obesity related cardio-metabolic diseases." (PMID 22952994, 2012). "FABP4 involved in the shuttling of FFA in adipocytes and modulation of lipid metabolisms was reported to be linked with obesity and insulin resistance." (PMID 22428043, 2012). "Among these, the lipocalin family proteins, FABP4, LCN2 and RBP4, have been identified as adipokines associated with obesity, type 2 diabetes and metabolic syndrome." (PMID 23119072, 2012). "Animal studies have shown that FABP4 knock-out mice are protected from the development of obesity-induced IR, impaired glucose tolerance and atherosclerosis, and their adipocytes have reduced lipolysis effectiveness." (PMID 23139800, 2012). "In obesity FABP4 expression was down-regulated (at both mRNA and protein levels), with its levels mainly predicted by ATGL and inversely by the HOMA-IR index." (PMID 23139800, 2012). "In this study we observed an inverse relationship between FABP4 expression and obesity, with a greater down-regulation with severe IR." (PMID 23139800, 2012). "Others studies have shown that FABP4 plasma concentrations are increased in patients with obesity, metabolic syndrome (MS), type 2 diabetes (T2D), familial combined hyperlipidemia, lipodystrophy syndromes and cardiovascular disease." (PMID 23139800, 2012). "In patients with a wide BMI range, we analyze FABP4 expression in adipose and hepatic tissues in the settings of obesity and insulin resistance." (PMID 23139800, 2012). "The FABP4 protein is considered to be a marker of lipid accumulation, obesity, and inflammation in morbidly obese women and is also known as adipocyte protein 2 (aP2)." (PMID 22046435, 2011). "In contrast, the circulating levels of leptin and FABP-4 are also enhanced in obesity and they are primarily released by fat cells of human adipose tissue." (PMID 20508843, 2010).
Obesity (continued). "FABP4 has been reported as a possible candidate gene for obesity since it was located within a quantitative trait loci (QTL) region contributing to the serum leptin levels in rat." (PMID 19077218, 2008). "In particular, FABP4 (A-FABP) binds FFAs, promoting lipid accumulation and the release of FFAs and adipocytokines, and elevated FABP4 levels in adipocytes have been strongly linked to obesity." (PMID 41551882, 2026). "FABP4 (fatty acid-binding protein 4) is a lipid chaperone and secreted adipokine linking dysregulated fatty acid handling with inflammation, cellular stress, and insulin resistance in obesity." (PMID 41683732, 2026). "Therefore, the upregulation of FABP4 within degenerated NPCs in the obesity state was controlled by the activation of the mTORC1/PS6 axis cascade." (PMID 40090836, 2025). "Considering this background, we can surmise that FABP4 plays an important role in the development of HF- and/or obesity-mediated PCa and, thus, may serve as a therapeutic target for PCa." (PMID 41226657, 2025). "However, knocking out FABP4 in mice significantly alleviated the progression of IVDD in the obesity state via regulating ECM homeostasis." (PMID 40090836, 2025). "Given that obesity is a major risk factor for IVDD and that FABP4 is a key mediator of obesity‐related metabolic and inflammatory processes, we hypothesise that FABP4 plays a critical role in obesity‐induced IVDD." (PMID 40090836, 2025). "Elevated levels of serum FABP4 have been reported not only in MASLD-HCC patients but also in obesity-associated breast cancer patients compared with nonobese patients." (PMID 41392988, 2025). "In addition, inhibiting the activation of the mTORC1 pathway decreased the production of both FABP4 and AGEs induced by an obesity state in vitro." (PMID 40090836, 2025). "It is hypothesized that FABP4 concentrations may serve as a valuable circulating Biomarker for certain metabolic disorders, including obesity, metabolic syndrome, and type 2 diabetes." (PMID 41034734, 2025). "The expression of FABP4 is increased in metabolic syndrome and in obesity." (PMID 39941741, 2025). "Mechanically, obesity promoted the expression of FABP4 via the mTORC1 pathway, and elevated FABP4 further promoted the secretion of advanced glycation end‐products (AGEs) within IVD tissue, which resulted in activated NF‐κB signalling pathway, extracellular matrix (ECM) imbalance, and angiogenesis." (PMID 40090836, 2025). "Nevertheless, whether obesity‐induced expression of FABP4 was regulated by the mTORC1 pathway remains elusive." (PMID 40090836, 2025). "Nevertheless, How FABP4 was regulated during obesity‐related IVDD and whether it plays a critical role during the progression of IVDD remains elusive." (PMID 40090836, 2025). "The results above indicated that FABP4 can be induced both in obesity and in an inflammatory state." (PMID 40090836, 2025). "Collectively, obesity‐induced FABP4 could effectively promote angiogenesis, possibly via the AGEs‐RAGE signalling pathway." (PMID 40090836, 2025). "In this study, we hypothesise that FABP4 is a critical mediator in obesity‐induced IVDD, contributing to ECM disequilibrium and angiogenesis, which exacerbate IVDD progression." (PMID 40090836, 2025). "Mechanistically, the regulated effect of adipocyte OGT on monocyte development may be mediated by NEFA-cluster of differentiation 36/fatty acid binding protein 4 (CD36/FABP4) pathway in HSCs in HFD-induced obesity." (PMID 40389445, 2025). "Future studies targeting these pathways in combination with FABP4 inhibition might also be possible therapeutic strategies for IVDD treatment in obesity‐related conditions." (PMID 40090836, 2025). "Additionally, NAC suppressed the expression of key obesity-related proteins, including fatty acid binding protein 4 (FABP4), monoamine oxidase A (MAOA), heat shock protein 70 (HSP70), aminoacylase-1 (ACY-1), and transketolase (TKT) in 3T3-L1 cells." (PMID 41149623, 2025).
Obesity (continued). "However, we demonstrate that obesity elevates FABP4 secretion from adipose tissue into the circulation, where extracellular FABP4 can directly target breast cancer cells, enhancing IL-6/STAT3/ALDH1-mediated tumor stemness and aggressiveness." (PMID 39054536, 2024). "This is especially important because secreted FABP4 was correlated with obesity-related breast cancer and its secretion from adipocytes in individuals with obesity is correlated with adipocyte hypertrophy, harmful effects on other tissues, and insulin resistance." (PMID 38388800, 2024). "However, there is limited knowledge regarding FABP4 expression in diabetes and obesity, especially about different age groups, genders, and ethnicities." (PMID 38731797, 2024). "In recent years, many studies have proposed that FABP4 could serve as a valid biomarker for obesity, and early detection of diabetic nephropathy, T2DM, and GDM." (PMID 38731797, 2024). "Future research and validation studies are crucial in elucidating the clinical significance of FABP4, both as a biomarker and as a therapeutic target for conditions such as diabetes and obesity, ultimately enhancing our ability to manage and address these pressing health concerns more effectively." (PMID 38731797, 2024). "Fatty acid binding protein 4 (FABP4), or adipocyte P2 (aP2), is an adipokine produced by adipocytes and macrophages that critically integrates metabolic and inflammatory responses from both types of cells to regulate obesity." (PMID 39324112, 2024). "BPA increases the number of adipocytes by regulating the expression of the FABP4, CD36, and PCSK1 genes; decreases the release of adiponectin and other adipokines; and disrupts adipocyte metabolism, thus increasing the risk of developing obesity." (PMID 39519574, 2024). "Leptin and FABP4 were highly expressed in WAT as obesity genes." (PMID 37073893, 2023). "Additionally, emerging evidence suggests that both SP1 and STAT3 can suppress the expression of pivotal genes implicated in adipocyte differentiation, including PPARγ, C/EBPα, and FABP4, thereby potentially restoring insulin sensitivity and mitigating obesity." (PMID 37445596, 2023). "Several in vitro and in vivo studies have indicated that Fabp4 may be a link between inflammation, obesity, and metabolic syndrome." (PMID 36839217, 2023). "The dCas9‐VP64 system can activate FABP4 and reverse obesity‐induced metabolic syndromes." (PMID 37356052, 2023). "In obesity, FABP4 expression increases in the liver and decreases in the adipose tissue." (PMID 36609276, 2023). "In future studies, it will be important to determine the effect of cellular sources of FABP4 on the pathogenesis of conditions such as cancer, obesity, and cardiovascular disease, where its circulating levels are regulated and known to be critical for systemic disease." (PMID 37279064, 2023). "Given the certain relationships between FABP4 and metabolic syndromes, these alternations may contribute to hepatic lipid accumulation, metabolic disturbances, and obesity in their later life." (PMID 37628833, 2023). "However, in the context of obesity where lipolysis is unrestrained because of insulin resistance, levels of FABP4 are chronically elevated in the circulation." (PMID 37172691, 2023). "It remains to be seen whether the relationships between circulating FABP4 and obesity, coronary heart disease, and various types of cancer are also occurring through similar indirect extracellular mechanisms." (PMID 37207357, 2023). "Elevated serum FABP4 levels in patients with obesity were previously reported." (PMID 36609276, 2023). "Fatty acid binding protein 4 (FABP-4) is a lipid-binding adipokine upregulated in obesity, which may facilitate fatty acid supply for tumor growth and promote insulin resistance and inflammation and may thus play a role in colorectal cancer (CRC) development." (PMID 37833736, 2023).
Obesity (continued). "FABP4 generally had higher affinity and selectivity for long-chain fatty acids and palmitic acid, a saturated fatty acid, that has relatively high affinity for FABP4 under a specific condition such as obesity-induced oxidative stress (Furuhashi, 2019)." (PMID 35391918, 2022). "Intracellularly, FABP4 has been shown to play a negative metabolic role in obesity and associated metabolic disorders via the regulation of lipolysis and lipogenesis." (PMID 35909571, 2022). "Accordingly, circulating FABP4 levels correlated with GSIS during obesity in humans." (PMID 35628332, 2022). "In addition, FABP4 contributes to the inflammatory response induced by macrophages in AT in the context of obesity." (PMID 35628332, 2022). "Since FABP4 is expressed in various cells in AT including adipocytes, preadipocytes, and macrophages, further studies are needed to use adipocyte- or macrophage-specific Cre mice to delineate the role of Omentin-1 in AT inflammation in obesity." (PMID 35909571, 2022). "Hepatocytes do not normally express FABP4, but expression occurs in obesity-associated HCC progression and promotes proliferation and migration of human HCC cell lines." (PMID 35721518, 2022). "FABP4 and fatty acids promote and regulate insulin secretion during obesity." (PMID 35647197, 2022). "Here, we review recent findings focused on the role of FABP4 in lipid metabolism, particularly lipid metabolism, in obesity, the possible molecular mechanism of carcinogenesis, and potential therapeutic targets, including breast, ovarian, liver, stomach, and pancreatic cancers." (PMID 36060264, 2022). "Recombinant FABP4 promotes inflammatory cytokine expression in 3T3-L1 adipocytes and in the AT of C57BL/6J mice via the p38/NF-κB pathway, further supporting its pro-inflammatory role in obesity-associated AT inflammation." (PMID 35909571, 2022). "Studies conducted on FABP4 null mice with induced obesity suggested that the metabolism of adipocyte fatty acids is a crucial component of the mechanisms leading to systemic insulin resistance in obesity." (PMID 35445019, 2022). "Although the underlying molecular mechanisms of Fabp4 expression and activity have not been fully elucidated, Omega-3 fatty acids were reported to decrease the expression and consecutive secretion of Fabp4, which had a positive effect on anti-obesity and reversal of insulin resistance." (PMID 36105184, 2022). "A recent study found that FABP4 could promote macrophage death by ceramide production, contributing to the chronic inflammation in obesity, which may also be a potential cancer-promoting mechanism." (PMID 36060264, 2022). "It has been shown that FABP4 may link fatty acid metabolism to the expression of TNFα and possibly play a key role in the development of obesity and IR." (PMID 35923855, 2022). "There is a redundant function between FABP4 and FABP5, as Fabp4 and Fabp5 (Fabp4/5 double-knockout (DKO) mice) exhibited a dramatic phenotype related to protection against obesity, insulin resistance, atherosclerosis, and fatty liver disease compared to Fabp4-/- or Fabp5-/- mice." (PMID 36553568, 2022). "The insulin resistance and obesity were notably inhibited in FABP4 knockout mice." (PMID 36670935, 2022). "This suggests that other tissues could be the primary contributors to elevated serum FABP4 levels in a state of obesity and insulin resistance." (PMID 35909571, 2022). "Similarly, obesity triggered increased expression of the liver-specific fatty acid transporter Fabp1 in hepatic cap ECs and of fatty acid transporters Fabp4, Cd36, Fabp5, Dbi and Lpl in art and ven ECs from AT." (PMID 36400935, 2022). "Our recent study demonstrated that growth differentiation factor 5 (GDF5) could promote white adipose tissue thermogenesis and alleviate high-fat diet- (HFD-) induced obesity in fatty acid-binding protein 4- (Fabp4-) GDF5 transgenic mice (TG)." (PMID 33542911, 2021).